NLRP3 (NLR family pyrin domain containing 3)
Diseases named in the same sentence as NLRP3 in open-access papers (continued):
Sharing a sentence is not in itself a finding about the gene and the disease.
Obesity (continued). "In humans, adipocyte but not SVF expression of NLPR3 inflammasome components and activation of the caspase-1 domain correlate with adiposity, suggesting that hypertrophic and dysfunctional adipocytes dominate the NLRP3 inflammasome-mediated response in obesity." (PMID 29186929, 2017). "In conclusion, our data suggests that the inhibition of NLRP3-inflammasome produces beneficial metabolic, inflammatory and could induce an autophagic adaptations in the heart of diet-induced obesity mice models." (PMID 29245937, 2017). "A recent report suggested that nucleotide-binding domain, leucine-rich containing family, pyrin domain-containig-3 (Nlrp3) inflammasome plays a pivotal role in obesity-induced chronic inflammation, and Nlrp3 inflammasome activates caspase-1, which induces the secretion of IL-1β." (PMID 28569167, 2017). "In this study, we evaluated whether the cardiac protective effects of nebivolol relied on attenuating NLRP3 activation in a juvenile-adolescent animal model of diet-induced obesity." (PMID 27686325, 2016). "NLRP3 is involved in obesity-induced cardiac remodeling and dysfunction." (PMID 27686325, 2016). "Besides, genetic or pharmacological inhibition of Nlrp3 inflammasome reduces infarct size and limits the development of diet-induced obesity." (PMID 26788246, 2016). "Given that IL-18 null mice exhibit hyperphagia, obesity and insulin resistance, the reduced levels of IL-18 may explain the observation that Nlrp3-/- mice fed a Western diet appeared to be more hyperphagic and tended to be heavier than WT mice." (PMID 27583382, 2016). "In this study, we tested, whether obesity-induced glomerular injury through Nlrp3 inflammsome activation in Asm+/+ and knockout mice." (PMID 26980705, 2016). "We had thus reasoned that the NLRP3 inflammasome is required for IL-1β production under obesity." (PMID 27708283, 2016). "Additionally neutrophils are a major site for expression of NLRP3 inflammasome components and a significant source of IL1β production, processes demonstrated to be important in obesity-induced insulin resistance." (PMID 26405763, 2015). "Moreover, ablation of NLRP3 in mice prevents obesity-induced inflammasome activation and the development of IR16." (PMID 26234821, 2015). "Thus, recent data show that NLRP3-/- knockout mice do not increase weight when fed a high fat diet, and that elimination of NLRP3 expression prevents obesity-induced caspase-1 cleavage as well as IL1β and IL18 activation." (PMID 25020064, 2014). "Indeed the importance of the NLRP3 inflammasome and caspase-1 activity in obesity-induced IR has been recently highlighted." (PMID 23675368, 2013). "Deficiency in any NLRP3 inflammasome component (NLRP3−/−, ASC−/−, Casp1−/−) has shown to be protective against the development of high-fat diet-induced obesity and improves glucose homeostasis in rodent models, and protective against chronic obesity-induced pancreatic damage." (PMID 23924318, 2013). "Despite the potential role of the NLRP3 inflammasome in obesity-induced inflammation and insulin resistance, it remains to determine whether its activation is a primary event in the disease that drives the inflammation." (PMID 23316186, 2012). "Interestingly, HFD‐NLRP3−/− mice showed no increase in the NLRP3 inflammasome‐related inflammatory parameters as well as an absence of enteric gliosis, thus providing evidence, for the first time, of a link among obesity, NLRP3 inflammasome activation and reactive gliosis." (PMID 39287080, 2025). "Intriguingly, despite clear evidence that NLRP3 inflammasome and IL-1β activity drive obesity and MAFLD, whether pyroptosis or other modes of programmed cell death, such as apoptosis and necroptosis, facilitate the demise of key cell types in tissues remains ambiguous." (PMID 39532538, 2025).
Obesity (continued). "Interfaces with obesity and associated metabolic disorders: Prospectively test whether targeting inflammation/energy metabolism (e.g., NLRP3/IL-6 pathways, statins/metformin/colchicine) disrupts the obesity–CHIP feedback loop and improves cardiometabolic outcomes." (PMID 41516113, 2025). "Indeed, increased levels of NLRP3 inflammasome were observed in obesity." (PMID 38895630, 2024). "However, knocking out the Nlrp3 or Caspase-1 gene suppresses obesity-induced fat depot." (PMID 38681198, 2024). "However, whether TXNIP/NLRP3 inflammasome activation contributes to the development of obesity cardiomyopathy remains unknown." (PMID 39604027, 2024). "Furthermore, whether the inhibition of NLRP3 inflammasome activation in cardiomyocytes improves obesity‐induced cardiac dysfunction remains unknown." (PMID 39604027, 2024). "Furthermore, in obesity, NLRP3 inflammasome can elicit chronic inflammation." (PMID 39273520, 2024). "Besides, PQQ also could protect hepatocyte from lipotoxicity and inflammation followed obesity via down-regulating the level of pro-inflammatory cytokines (NLRP3, IL-6, TNF and IL-1β)." (PMID 37935689, 2023). "Besides the molecular and cellular mechanisms mentioned earlier, obesity has also been connected to the activation of the nucleotide-binding oligomerization domain-like receptor protein 3 (NLRP3) inflammasome, a critical intracellular signaling complex involved in the innate immune response." (PMID 37474953, 2023). "Moreover, the NLRP3 rs10754558 polymorphism, which leads to higher production of IL-1β and thus resembles a gain-of-function mutation, and the IL1B rs16944 polymorphism have been associated independently by various groups with T2DM and obesity." (PMID 37239938, 2023). "Similarly, obesity-related lipotoxic ceramides activate caspase-1 in an NLRP3-dependent manner." (PMID 38069047, 2023). "Transferring the data generated mainly in mice to humans would mean that inhibition of the NLRP3 inflammasome or IL-1β, as promising as it appears for treating obesity-associated morbidities, is not a suitable option for prevention of adiposity and its related metabolic diseases." (PMID 37239938, 2023). "Furthermore, it was shown that metabolic dysfunctions, including obesity, insulin resistance, adipose tissue inflammation, lipid accumulation, and dysregulated glucose metabolism, can trigger NLRP3 inflammasome activation in various tissues, including the liver and the brain." (PMID 38068904, 2023). "In this context, the expression levels of NLRP3 and IL-1β are increased in the VAT of obese patients with metabolic alterations when compared with obese patients without these alterations, suggesting that the NLRP3 inflammasome has an important role in metabolic alterations associated with obesity." (PMID 37049561, 2023). "Accordingly, the NLRP3 inflammasome pathway as well as the resulting production of the master cytokine IL-1ß might contribute to clinically relevant consequences of inflammation in obesity." (PMID 35931812, 2022). "The NOD-like receptor (NLR) family pyrin domain–containing protein 3 (NLRP3) inflammasome is an important component of the inflammatory process and is involved in various inflammatory disorders, such as Alzheimer’s disease, multiple sclerosis, type 2 diabetes, and obesity." (PMID 36017888, 2022). "However, aberrant activation of NLRP3 inflammasome has been related to obesity." (PMID 36501129, 2022). "Besides counteracting obesity, perhaps activating the H1 receptor by using betahistine, or another H1 receptor agonist, could also inhibit NLRP3/caspase-1 signaling and thus pyroptosis and brain volume loss induced by chronic antipsychotic treatment." (PMID 35615587, 2022). "Therefore, it is plausible to surmise that the reduction in obesity-induced ATM and systematic inflammation in the HF + HVD group might be associated with the inhibitory effect of vitamin D on NLRP3-related IL-1β levels." (PMID 36142842, 2022).
Obesity (continued). "Nutrient excess in obesity leads to an accumulation of metabolic stress molecules, such as FFAs, cholesterol crystals, glucose, or amyloid polypeptides, which serve as the second activation signal to promote the assembly and activation of the NLRP3 inflammasome." (PMID 33535473, 2021). "Finally, we address pharmacological NLRP3 inhibitors that may have a therapeutical use in obesity-related metabolic alterations." (PMID 33806797, 2021). "However, whether exercise and exercise-induced myokines can regulate obesity-induced NLRP3 inflammasome activation in adipose tissue remains unclear." (PMID 34943988, 2021). "In vitro, we tested whether APPL1 deficiency has any effect on inflammasome activation induced by palmitic acid, the most abundant saturated fatty acid with marked elevation in obesity and is known to induce NLRP3 inflammasome activation by inhibiting autophagy/mitophagy." (PMID 34789781, 2021). "Hence, NLRP3 blockade in mice protects against HFD-induced obesity and insulin resistance." (PMID 33546399, 2021). "For instance, in type II diabetes, the aberrant activity of the NLRP3-inflammasome complex leads to IL1β secretion and caspase-1 activation that impair pancreatic β-cell function, adipocyte function and insulin sensitivity, promoting obesity and insulin resistance." (PMID 34685542, 2021). "Because the NLRP3 inflammasome is activated in human mesenchymal stem cells via lipopolysaccharide and palmitic acid, and plasma levels are increased in the context of obesity, Hcy might be one of the mediators involved in obesity-induced insulin resistance." (PMID 33643070, 2021). "Together, these findings suggest that the NLRP3 inflammasome, HMGB1, TLR4, and possibly some other mediators might serve as promising therapeutic targets to counter visfatin-mediated vascular injury associated to obesity." (PMID 33182523, 2020). "In mouse models, genetic or pharmacological inhibition of NLRP3 activation pathways or IL-1β prevents adipose tissue dysfunction, including inflammation, fibrosis, defective lipid handling and adipogenesis, which in turn alleviates obesity and its related metabolic disorders." (PMID 32545355, 2020). "In sum, these results have suggested that activation of NLRP3-inflammasome/IL-1β signalling could activate neuroinflammatory response and impair synaptic plasticity, leading to cognitive impairment in diet-induced obesity or diabetic condition." (PMID 33379163, 2020). "Hence, therapeutics targeting the NLRP3 inflammasome could be employed in the treatment of T2D and obesity because considerable numbers of studies have shown the effectiveness of this strategy." (PMID 32012695, 2020). "Indeed, genetic ablation of NLRP3 or caspase-1 prevents obesity-induced adipocyte hypertrophy, yet whether this is due to changes in adipogenesis, lipolysis and/or energy metabolism remains to be further clarified." (PMID 32545355, 2020). "However, the combination of overweight/obesity and hypertension may be even worse, strongly stimulating NLRP3 signaling." (PMID 33114648, 2020). "The SARS-CoV-2 infection could potentiate or accelerate the pre-existing systemic inflammatory state of individuals with obesity, via the NLRP3 inflammasome activation and the release of pro-inflammatory cytokines from cells trough Gasdermin-pores commonly found in cell death by pyroptosis." (PMID 33193349, 2020). "Dietary saturated fatty acids (SFAs), whose intake is strongly associated with an increased risk of obesity, have been identified as potent priming agents of the NLRP3 inflammasome via TLR4 in DCs, resulting in elevated expression of pro-IL-1β, caspase-1, TLR4 and NLRP3." (PMID 32545355, 2020). "With this refined murine model of diet-induced obesity, we sought to investigate the potential benefit of global A2 deletion on western diet-induced retinopathy with regards to increased inflammation via activation of the NLRP3 inflammasome pathway and its effects on retinal histology and function." (PMID 31979105, 2020).
Obesity (continued). "We and other have suggested that NLRP3 could be a link between obesity and metabolic and inflammatory stress, and our findings herein suggest several molecular pathways that could be related to NLRP3-driven inflammation during obesity, including changes in gut microbiota." (PMID 33273482, 2020). "Moreover, plasma levels of mature IL-18, activated by the NLRP3 inflammasome, and TNF, a cytokine that could be activated down-stream to NLRP3 activation, were increased with obesity and markedly reduced in inflammasome deficient mice." (PMID 31379826, 2019). "Collectively, our data suggests that obesity drives cardiac hypertrophy per se, while systemic inflammation and metabolic dysfunction promotes adverse effects on cardiac remodeling and function, and these systemic effects were attenuated in Nlrp3−/− and Asc−/− (Pycard−/−) mice." (PMID 31379826, 2019). "However, it remains unclear how physical activity regulates NLRP3 inflammasome‐mediated vascular dysfunction in obesity." (PMID 29932503, 2018). "Moreover, targeting the inflammasome could also be beneficial to offset some of the side effects of glucocorticoids such as obesity and glucose intolerance, as NLRP3 overactivation plays a role in these metabolic disorders." (PMID 29558930, 2018). "A causal mechanism by which obesity promotes the progression of breast cancer via the NLRC4 inflammasome activation has been recently described but no results showing the impact of NLRP3 in obesity-associated CRC have been reported." (PMID 30619282, 2018). "However, the effect of physical activity on NLRP3 inflammasome activation‐associated vascular function in obesity is not tested elsewhere." (PMID 29932503, 2018). "Notably, recent studies have linked the activation of the NLRP3 inflammasome to different metabolic diseases including obesity, metabolic syndrome, T2D and cardiovascular alterations and the role of NLRP3 in cancer, especially in inflammation-induced cancers, has been extensively explored." (PMID 30619282, 2018). "Moreover, direct participation of NLRP3 in obesity has been confirmed in studies that have shown that in gene-deficient mice fed with a high-fat diet, activation of caspase-1 and expression of pro-IL-1b in adipose tissue, and serum loss of IL-18 compared to the wild-type phenotype is reduced." (PMID 28319103, 2017). "Thus, cAMP/PKA-signaling regulated by PDE3B in adipose tissue and potential targeting of caspase-1 activation through NLRP3 inflammasome, may be a new therapeutic target for the development of anti-obesity and anti-inflammatory drugs." (PMID 27321128, 2016). "In this study, we tested the hypothesis that Nlrp3 inflammasome activation in endothelial cells could be a triggering mechanism elicited by free fatty acids that contributes to the development of vasculopathy in obesity." (PMID 27689324, 2016). "However, it remains unknown how the Nlrp3 inflammasomes is activated and thereby results in glomerular injury during obesity." (PMID 26980705, 2016). "Thus, targeting cathepsin B/Nlrp3 inflammasome signaling axis could be a potential therapeutical strategy for treating cardiovascular diseases in obesity." (PMID 27689324, 2016). "However, the observation that the NLRP3 inflammasome is activated by fatty acids and ceramides suggests that the lipotoxic environment in obesity might trigger its activation." (PMID 23316186, 2012). "Thus, the activation of NLRP3 inflammasome in obesity might be related to the oxidative stress that develops in the different metabolic tissues." (PMID 23316186, 2012). "On the other hand, caspase-1 activity in NLRP3-deficient obese mice decreases but is not abolished in the presence of inflammasome inducers, suggesting that inflammasome “priming” plays a role at least in the pathophysiology of obesity." (PMID 22768222, 2012).
Obesity (continued). "In an obesity-related study, AMPK phosphorylates the SUCLA2 metabolic enzyme to restrict glutaminolysis, thereby reducing succinate accumulation and blocking NLRP3 inflammasome activation, which ultimately attenuates pro-IL-1β transcription." (PMID 41508030, 2026). "The modulation of the NLRP3 inflammasome and monocyte chemokine receptors induced by high-intensity interval training (HIIT) in individuals with obesity is still poorly understood." (PMID 41729927, 2026). "Proteins of the nucleotide-binding and oligomerization domain (NOD)-like receptor (NLR) family are a group of PRR, and some of them, including NLRP3, NLRP6 NLRC1, NLRC2, NLRC5, and NLRP12, promote inflammation in obesity." (PMID 40149869, 2025). "6-Shogaol inhibited IL-1β secretion by blocking NLRP3 inflammasome activation and reduced TNF-α levels, demonstrating a relevant anti-inflammatory effect in the context of obesity." (PMID 40733199, 2025). "In mouse diet‐induced obesity models, the brain penetrant NLRP3 inhibitor NT‐0796 enhances and sustains the efficacy of the GLP‐1RA semaglutide, leading to a complete reversal of obesity." (PMID 40304241, 2025). "In the context of high-fat diet-induced obesity, the acetylation of K255 on the α subunit of hydroxyl-CoA dehydrogenase triggers the mitochondrial localization of ASC, thereby activating the NLRP3 inflammasome and contributing to myocardial fibrosis." (PMID 40307577, 2025). "Studies have found that chronic inflammation plays a crucial role in obesity-related cardiomyopathy, activating the NOD-like receptor protein 3 (NLRP3) inflammasome and thereby triggering pyroptosis." (PMID 40430076, 2025). "In summary, our data indicate that in the HFD-induced obesity model, there are heightened activation of RAS and NLRP3 inflammasome signaling, alongside increased CCK activity." (PMID 38762465, 2024). "PD-L1 gene transcription is enhanced by activation of cGAS-STING, NF-κB, the NLRP3 inflammasome, and IFN-γ/JAK/STAT pathways, which leads to impaired immunosurveillance and decreased clearance of senescent cells during aging and obesity." (PMID 39063184, 2024). "A study found that exercise decreased protein expression of inflammasome components (NLRP3 and caspase-1) in bone marrow-derived macrophages (BMDM) and AT isolated from mice with diet-induced obesity." (PMID 38681198, 2024). "During obesity, senescent cells develop an inflammatory UPR in the ER directed to continuous activation of the NLRP3 inflammasome." (PMID 39063184, 2024). "Our meta-analysis provides further evidence for the upregulation of the NLRP3 inflammasome and its related components in obese and PCOS individuals, which is indicative of a possible role of this inflammasome in obesity and PCOS-related chronic inflammation." (PMID 37446154, 2023). "By inhibiting the TXNIP/NLRP3 pathways and improving autophagic clearance, transdermal application of Vera@CLCMP patches alleviated obesity-induced insulin resistance and hepatic steatosis." (PMID 36670488, 2023). "We found that blood lipid levels increased with age, and it has been proven that the NLRP3 inflammasome is activated by high levels of LDL-C and TC, while the deletion of NLRP3 prevents lipid deposition in obesity." (PMID 37720530, 2023). "Earlier, it was proposed that FFAs, whose levels are increased in obesity, can activate NF-κB via TLR4 in macrophages and adipocytes and thus lead to NLRP3 inflammasome priming." (PMID 37239938, 2023). "Further exploration of FA effects on TLR4/NF-κB signaling and NLRP3 inflammasome–induced pyroptosis and the relationship between the two signaling pathways, may help to elucidate the roles of different FA mechanisms in OA, revealing possible intervention targets for obesity-related OA." (PMID 35571243, 2022).